PALB2 (partner and localizer of BRCA2)
Diseases named in the same sentence as PALB2 in open-access papers (continued):
Sharing a sentence is not in itself a finding about the gene and the disease.
breast cancer (continued). "Somatic mutation analysis of the WES data of 16 PALB2-associated breast cancers revealed a median of 113.5 (range 59–269) somatic mutations per case, of which 82.5 (range 37–195) were non-synonymous." (PMID 31428676, 2019). "In contrast, PALB2 somatic mutations as a mechanism of bi-allelic inactivation were significantly more frequent in the PALB2-associated breast cancers from this series (31%; 5/16; P = 0.00006, Fisher’s exact test)." (PMID 31428676, 2019). "The eight PALB2-associated breast cancers analyzed by MSK-IMPACT displayed a median of 3 (range 0–5) somatic mutations per case, of which 2 (range 0–4) were non-synonymous." (PMID 31428676, 2019). "To date, most pathogenic PALB2 mutations reported in breast cancer (BC) patients are truncating mutations distributed throughout its coding region." (PMID 31586400, 2019). "All published estimates of penetrance of PALB2 mutations (recently reviewed by us) are comparable to the breast cancer risk associated with mutations in BRCA2: 45% (95% CI, 31–56%)." (PMID 29052111, 2018). "Results from logistic regression analysis confirmed the association of PALB2 mutations with family history of PC (P = .029) or breast cancer (P = .0056) and the association of CHEK2 mutations with family history of colorectal cancer (P = .014)." (PMID 31497750, 2018). "Mutations in ATM, BRCA2, and PALB2 were also more frequent in patients with PC with a family history of breast cancer (first- or second-degree relative)." (PMID 31497750, 2018). "In five patients (5 of 83; 6% of cohort), we detected causative pathogenic variants in established hereditary breast cancer susceptibility genes (i.e., PALB2, CHEK2, ATM)." (PMID 30086788, 2018). "Herein, we have found that high PALB2 expression was significantly associated with poor overall survival in stage III breast cancer patients and in patients with lymph node metastasis involved (N1, N2 or N3)." (PMID 29321957, 2018). "The BRCA2:p.Trp31Gly and the PALB2:p.Pro1088Ser variants were originally identified in two different Italian breast cancer probands born in Milano and Bergamo, respectively and are located in the BRCA2-PALB2 interacting domains." (PMID 30410870, 2018). "For instance, rs139362268, a synonymous variant of PALB2, is related to breast cancer and pancreatic cancer." (PMID 29617790, 2018). "The two missense variants BRCA2:c.91T >G (p.Trp31Gly) and PALB2:c.3262C >T (p.Pro1088Ser) were detected in two breast cancer probands originally ascertained at Breast Cancer Units of Institutes located in Milan and Bergamo (Northern Italy), respectively." (PMID 30410870, 2018). "This study is consistent with previous reports that PALB2:c.509_510del and PALB2:c.172_175del are recurrent mutations associated with breast cancer predisposition in Polish women with a family history of the disease." (PMID 29052111, 2018). "Here, we evaluated the prognostic effects of PALB2 with tissue microarray specimens of 117 female breast cancer patients, and determined the potential underlying mechanisms in cell models." (PMID 29321957, 2018). "Recent studies showed that women who carry mutations in the PALB2 gene are at similar breast cancer risks as those who carry mutations in BRCA2." (PMID 29456628, 2018). "Loss of function PALB2 pathogenic variants confer a breast cancer risk of 35% by age of 70, that is comparable to that conferred by BRCA2 pathogenic variants." (PMID 30410870, 2018).
breast cancer (continued). "Our study contributes to the accumulating evidence indicating that PALB2 should be included in genetic testing for breast cancer susceptibility in these populations to enhance risk assessment and management of women at high-risk of developing breast cancer." (PMID 29052111, 2018). "WES was performed on four women and identified RNASEL:p.Glu265* in III.8, who is known to carry the PALB2 mutation and had two primary diagnoses of breast cancer at age 36 and 45 years." (PMID 29422015, 2018). "The possibly high risk of breast cancer makes bilateral prophylactic mastectomy a potential option for women with PALB2 mutations." (PMID 30174725, 2018). "The relevant variant was detected in four of seven family members, two of whom had been diagnosed with a typically associated tumor (breast cancer in PALB2 and BRCA1 variants)." (PMID 29909963, 2018). "PALB2 mutation is associated with increased breast cancer risk; however, PALB2 mutation is rare in sporadic breast cancer cases and little is known about PALB2 expression in breast cancer." (PMID 29321957, 2018). "Germline pathogenic variants in BRCA1, BRCA2 and PALB2 DNA repair genes are associated with high risk of developing breast cancer." (PMID 30410870, 2018). "Breast cancer risk associated with carrying PALB2 loss-of-function mutations is now well established." (PMID 29052111, 2018). "Genetic modifiers of risk for carriers of high-risk mutations in other breast cancer susceptibility genes, such as PALB2, are yet to be described." (PMID 29422015, 2018). "Loss-of-function germline mutations in the PALB2 gene are associated with an increase of breast cancer risk." (PMID 29052111, 2018). "Women with PALB2 mutations have up to a fivefold increase in the risk of developing breast cancer compared to the general population." (PMID 30174725, 2018). "In conclusion, we firstly evaluated the expression of PALB2 in sporadic breast cancer and the association between PALB2 expression and prognosis of the breast cancer patients." (PMID 29321957, 2018). "The presence of PALB2 mutations is associated with increased breast cancer risk (odds ratio [OR] = 4.4, 95% confidence interval [CI] 2.30 to 8.37; P < 0.0001)." (PMID 29678143, 2018). "For female carriers of the PALB2 mutation, the risk of developing breast cancer has been estimated at 14% by 50 years of age, and 35% by 70 years of age." (PMID 29023372, 2017). "In breast cancer families with both female and male breast cancer, PALB2 mutation rates increased to 6.7% in a UK study and to 9.0% in a Spanish study." (PMID 28279176, 2017). "For example, women with inherited causative variant in the Fanconi anemia genes BRIP1 and PALB2 have a 20–50% lifetime risk of breast cancer." (PMID 29093764, 2017). "PALB2 c.1592delT mutation has been observed at 0.7–0.9% frequency among Finnish unselected breast cancer patients and at 2.0–2.7% frequency among familial patients and is associated with an aggressive breast tumour phenotype." (PMID 28874143, 2017). "Less than a year later, PALB2 had already been recognized as an important gene for breast cancer susceptibility and, later, also for pancreatic cancer." (PMID 28858227, 2017).
breast cancer (continued). "One of the key players in HR is the partner and localizer of breast cancer susceptibility protein 2 (PALB2), which is mutated in a subset of breast cancer and Fanconi Anaemia patients (FANCN)." (PMID 28240985, 2017). "Of note, the PALB2 germline mutation (p.E837K) identified in our study was previously reported in familial breast cancer." (PMID 29190888, 2017). "The other recurrent PALB2 mutation, c.172_175delTTGT, was identified in breast cancer patients from the Czech Republic and Poland." (PMID 28279176, 2017). "PALB2 mutations among MBC patients are relatively rare (0.8%) in the US population but have been associated with a significantly increased risk of male breast cancer." (PMID 28874143, 2017). "PALB2 is a tumor suppressor gene; its alteration of which was known to predispose to childhood Wilms’ tumor and medulloblastoma as well as breast cancers." (PMID 29190888, 2017). "The first breast cancer family-based association study estimated that a relative risk of 2.3 (95% CI: 1.4–3.9) is conferred by mutations of PALB2." (PMID 28279176, 2017). "To date, approximately 50 truncating mutations in PALB2 have been detected in breast cancer families worldwide." (PMID 28279176, 2017). "Recent work has increased the precision of breast cancer risk estimates for PALB2 mutation carriers providing some new information with clinical utility." (PMID 27099641, 2016). "Ten-year survival for women with breast cancer and a PALB2 mutation was 48.0 % (95 % CI, 36.5 %–63.2 %), compared with 74.7 % (95 % CI, 73.5 %–75.8 %) for non-carriers (hazard ratio for death 2.27, 95 % CI, 1.64–3.15; p < 0.0001)." (PMID 27099641, 2016). "We identified the PALB2 mutation c.509_510delGA in two unrelated patients (1.7 %), both of whom were diagnosed with breast cancer before age 50 and had one affected relative." (PMID 26843898, 2016). "The family histories of the case carriers, unselected for age or family history, reported in Northern Finland, were used to estimate PALB2 c.1592delT to be associated with a 40 % (95 % CI, 17 %–77 %) risk of breast cancer to the age of 70 years." (PMID 27099641, 2016). "Some other data indirectly supports a likely worse outcome for PALB2 mutation carriers, including the propensity in some population for PALB2 mutation-associated breast cancers to be of higher grade, including triple negative." (PMID 27099641, 2016). "By pooling international resources, the PALB2 Interest Group estimated that the relative risk of ovarian cancer and male breast cancer for PALB2 mutation carriers was 2.31 (95 % CI, 0.77–6.97; P = 0.18) and 8.30 (95 % CI, 0.77–88.56; P = 0.08) respectively." (PMID 27099641, 2016). "Mutations in PALB2 make a small contribution to heritable breast cancer susceptibility in most populations." (PMID 27099641, 2016). "In a study of 144 Polish breast cancer families, the mutation was identified in 1.4 % and accounted for 50 % of all PALB2 mutation carriers." (PMID 26843898, 2016). "Internationally, tens of thousands of women, including those who have gone direct to the test provider, have had genetic tests for PALB2 mutations in the context of breast cancer susceptibility." (PMID 27099641, 2016). "PALB2 has now firmly taken its place with the small number of bona fide breast cancer susceptibility genes." (PMID 27099641, 2016). "Breast cancer risk associated with carrying a PALB2 loss-of-function mutations is now established but research is urgently needed to extend this knowledge to an understanding of clinical outcomes for carriers." (PMID 27099641, 2016). "ROVER was developed in tandem with Hi-Plex and has been used successfully to screen for genetic mutations in the breast cancer predisposition gene PALB2." (PMID 27083325, 2016). "PALB2 now plays a legitimate role in breast cancer clinical genetics practice and takes a valid place on breast cancer predisposition gene panel tests." (PMID 27099641, 2016).
breast cancer (continued). "PALB2 has recently been reported to confer a breast cancer risk comparable to that of BRCA2 mutations, indicating the need to include it in the clinical diagnostics along with BRCA1 and BRCA2 mutation testing." (PMID 26820313, 2016). "Reports from a variety of populations consistently estimate that PALB2 mutations are associated with increased risk for breast cancer (e.g., OR 3.94, 95 % CI, 1.5–12.1)." (PMID 27099641, 2016). "Tens of thousands of women worldwide have now had genetic tests for PALB2 mutations in the context of breast cancer susceptibility." (PMID 27099641, 2016). "It is now well established that women who carry mutations in the PALB2 gene are at similar breast cancer risks as those who carry mutations in BRCA2) making many rethink the appropriateness of the initial “moderate or intermediate risk gene” label." (PMID 27099641, 2016). "Among families with three or more breast cancers, the detection rate of 509_510delGA and 172_175delTTGT PALB2 mutations increases to 4.6 %." (PMID 26843898, 2016). "Heterozygous loss-of-function mutations in PALB2 have been shown to be a risk factor for breast cancer, while PALB2 germline mutations have recently been associated with a poor outcome." (PMID 28027327, 2016). "As few studies have been conducted within unselected breast cancer cases, estimation of the age-specific cumulative risk (penetrance) of breast cancer associated with PALB2 mutations has been limited." (PMID 27099641, 2016). "Supported by other similar observations, some recommend that both family history and PALB2 genotype should be considered together for clinical breast cancer risk management." (PMID 27099641, 2016). "Both PALB2 mutation-associated breast cancers were ER/PR-positive invasive ductal carcinomas with coexisting ductal carcinoma in situ." (PMID 26843898, 2016). "Mutations of PALB2 hinder its ability to properly synthesize DNA, leading to breast cancer due to mutations in the DNA." (PMID 30460281, 2016). "Monoallelic (heterozygous) mutations in PALB2 cause an increased risk for breast cancer, with the highest risks for cases with a family history of breast cancer." (PMID 26484312, 2015). "A total of 4 deleterious PALB2 mutations were identified in 152 breast cancer patients with a prevalence of about 2.6 % (4/152)." (PMID 26489409, 2015). "Similar to the mutation spectrum observed in BRCA1/2, protein truncating mutations in PALB2 are associated with breast cancer." (PMID 26489409, 2015). "With regards to genetics, PALB2 (Partner And Localizer of BRCA2) was presented as a new high-risk breast cancer gene identified and the reasons why it should be added to genetic testing for BRCA1/BRCA2 were clearly explained." (PMID 25729421, 2015). "Here, we present the identification of PALB2 mutations in patients with inherited breast cancer from Xinjiang region of China." (PMID 26489409, 2015). "In the 152 patients, 95 cases had family history of breast cancer, three patients were identified deleterious mutations, the PALB2 mutation prevalence was 3.2 % (3/95)." (PMID 26489409, 2015). "At this point, there is insufficient evidence about new primary breast cancer risk associated with PALB2 mutations to recommend consideration of risk-reducing bilateral mastectomy, especially in a post-menopausal patient." (PMID 26484312, 2015). "It has been discovered that heterozygosity for loss-of-function mutations at PALB2 increases risk of developing breast cancer two- to ninefold." (PMID 26489409, 2015). "A previous study conducted in a South African cohort revealed a pathogenic PALB2 mutation in 2 % of early onset white breast cancer patients." (PMID 26577449, 2015). "Our data strongly support PALB2 as a breast cancer predisposition gene when considering truncating mutations." (PMID 26283626, 2015).
breast cancer (continued). "The patient with the PALB2 mutation, c.64G>A, was diagnosed with bilateral breast cancer and had positive family history." (PMID 26489409, 2015). "The aim of this study is to understand the status of PALB2 mutations among Chinese high-risk breast cancer patients in a multi-ethnic region in China." (PMID 26489409, 2015). "As previously observed, triple-negative breast cancers tend to harbor BRCA1/2 mutation which appears to be slightly overrepresented in PALB2-related breast cancers." (PMID 26489409, 2015). "The low frequency of truncating variants in controls supports PALB2 as a high-penetrance breast cancer predisposing gene." (PMID 26283626, 2015). "Recently it was suggested that the risk to develop breast cancer for PALB2 mutation carriers is as high as the risk borne by BRCA2 mutation carriers." (PMID 26577449, 2015). "So we think that PALB2 mutations contribute to a small fraction of bilateral breast cancer in the Xinjiang region of China." (PMID 26489409, 2015). "Germline mutations in PALB2 confer a 2–5 fold increase in breast cancer risk and germline mutations have been recently found in African American breast cancer patients." (PMID 25869442, 2015). "Two individuals (UTSW9 and UTSW36) harbored nonsense mutations in PALB2, which has recently been reported to result in an elevated risk for breast cancer similar to BRCA2 mutations." (PMID 26023681, 2015). "Inherited PALB2 mutations associated with increased risks of developing breast cancer have been identified in families from many parts of the world, including China." (PMID 26489409, 2015). "To date, only a few studies have been reported on PALB2-associated breast cancer in China, and the revaluated studies only involved ethnic Han Chinese." (PMID 26489409, 2015). "A small number of the pedigrees reported in the literature to carry protein truncating PALB2 mutations included cases of male breast cancer." (PMID 26489409, 2015). "Germline mutations in PALB2 gene make a small contribution to the heritable breast cancer susceptibility and increased risk for breast cancer." (PMID 26489409, 2015). "Carriers of deleterious PALB2 mutations have a moderate to high risk of breast cancer and also an increased risk of pancreatic cancer and ovarian cancer." (PMID 26082817, 2015). "As with BRCA2, germ line mutations of PALB2 confer increased risk of breast cancer as well as ovarian and pancreatic cancer." (PMID 26082817, 2015). "Germline mutations in PALB2 gene make a small contribution to heritable breast cancer susceptibility." (PMID 26489409, 2015). "In Australia, early studies identified PALB2 c.3113G > A (p.Trp1038*) as a recurring truncating mutation among familial breast cancer index cases, and established the enrichment of c.3113G > A in cases compared to controls." (PMID 26283626, 2015). "In a recent report in the new England Journal of Medicine, women with inherited loss-of-function mutations in the PALB2 gene were found to be more than nine times as likely to develop breast cancer, compared to the general population." (PMID 26489409, 2015). "Germline mutations in PALB2 have been identified in approximately 1% of familial breast cancer (BC) in several populations." (PMID 25636233, 2015). "Consistent with this, another study reported that 4.8% of families with both cancer types harboured truncating PALB2 mutations, higher than the rate previously reported in studies investigating breast cancer alone." (PMID 24949998, 2014). "From this observation, germline PALB2 mutations were subsequently shown to be associated with breast cancer risk." (PMID 24949998, 2014). "In a third study, PALB2 p.Y1183X was associated with breast cancer in a person presenting with two primary breast cancers." (PMID 24949998, 2014).